ZNF385A (zinc finger protein 385A)
Description:
RNA-binding protein that affects the localization and the translation of a subset of mRNA. May play a role in adipogenesis through binding to the 3'-UTR of CEBPA mRNA and regulation of its translation. Targets ITPR1 mRNA to dendrites in Purkinje cells, and may regulate its activity-dependent translation. May also bind CCNB1 mRNA. May also regulate the ubiquitination and stability of CDKN1A promoting DNA damage-induced cell cycle arrest. Also plays a role in megakaryocytes differentiation.
Synonyms: HZF; RZF; ZNF385; DKFZp586G1122; ZFP385
Tractability: PROTAC: UniProt records ubiquitination sites on it; its protein half-life has been measured.
Gene: Protein-coding gene on chromosome 12 (54,369,129 to 54,391,307, reverse strand). Ensembl gene ENSG00000161642.
Subcellular location: Cytoplasm; Nucleus, nucleolus; Cell projection, dendrite
Subcellular location (Human Protein Atlas): Cytosol; Nucleoplasm
Pathways (Reactome):
Cell Cycle: Transcriptional activation of cell cycle inhibitor p21
Gene Ontology:
Molecular function: RNA binding; mRNA 3'-UTR binding; nucleic acid binding; zinc ion binding
Biological process: apoptotic process; DNA damage response; megakaryocyte development; mRNA localization resulting in post-transcriptional regulation of gene expression; positive regulation of fat cell differentiation; regulation of cytoplasmic translation
Cellular component: chromatin; cytosol; neuronal cell body; nucleoplasm; nucleus; cytoplasm; dendrite; nucleolus
Genetic constraint (gnomAD): Loss-of-function variants: 14 observed, 29.71 expected, observed/expected ratio (o/e) 0.47, 90% interval 0.31 to 0.74. The upper end of that interval is the gene's LOEUF score, 0.74, which puts it in group 3 of 6, group 1 being the genes least tolerant of losing a copy. Missense variants: 406 observed, 424.74 expected, observed/expected ratio (o/e) 0.96, 90% interval 0.88 to 1.04. Synonymous variants: 197 observed, 176.07 expected, observed/expected ratio (o/e) 1.12, 90% interval 1 to 1.26.
Homologues: Orthologues: chimpanzee ZNF385A (99% identical), pig ZNF385A (98% identical), guinea pig ZNF385A (96% identical), rat Zfp385a (96% identical), mouse Zfp385a (96% identical), rabbit ZNF385A (84% identical), macaque ZNF385A (84% identical), dog ZNF385A (82% identical), zebrafish znf385a (64% identical), tropical clawed frog znf385a (62% identical), Drosophila melanogaster dbf (23% identical), Drosophila melanogaster CG1231 (18% identical). Paralogues in human: ZNF385D (50% identical), ZNF385B (48% identical), ZNF385C (40% identical), ZMAT3 (14% identical), ZMAT1 (12% identical), ZNF346 (12% identical), ZMAT4 (11% identical), ZMAT2 (9% identical), KRCC1 (5% identical).
Diseases named in the same sentence as ZNF385A in open-access papers:
ZNF385A is named in the same sentence as 13 diseases in open-access papers, as found by Europe PMC text mining. Sharing a sentence is not in itself a finding about the gene and the disease. The quoted sentences say what the papers report.
chronic hepatitis (1 paper, 2023). An active inflammatory process affecting the liver for more than six months. "We downloaded the gene expression profiles of 94 samples covering different stages of HCC from GSE89377, found that the expression of ZNF385A and ZNF346 gradually increased from chronic hepatitis to liver cirrhosis and HCC." (PMID 36834567, 2023). "Finally, a dataset covering the different stages of hepatocellular carcinoma showed a trend of progressive increase in ZNF385A and ZNF346 expression, from chronic hepatitis to hepatocellular carcinoma." (PMID 36834567, 2023).
cognitive decline (1 paper, 2020). "Brain gene expression of ZNF385A and DNA methylation dysregulations are implicated in the Alteration of brain tissue properties associated with late-life cognitive decline above and beyond the influence of common neuropathologic conditions." (PMID 31934508, 2020).
liver cancer (1 paper, 2023). An epithelial or non-epithelial malignant neoplasm that arises from the liver. "By performing TIDE analyses and survival analyses in one liver cancer and one urothelial cancer cohort receiving anti-PD-1/anti-PD-L1 therapy, we observed that ZNF385A and ZNF346 performed well in predicting the responses to ICI therapy." (PMID 36834567, 2023). "In conclusion, ZNF385A and ZNF346 are promising candidate biomarkers for the diagnosis, prognosis, and response to immunotherapy in HCC, and this study may help to understand the tumor microenvironment (TME) of liver cancer, and to develop new therapeutic targets." (PMID 36834567, 2023).
serous ovarian carcinoma (1 paper, 2018). "High expression of VEGFA and ZNF385A correlate with poor survival of patients with serous ovarian carcinoma." (PMID 29503225, 2018).
tumor (3 papers, 2018 to 2023). "Some of these genes, including GDF15, TGM2, VEGFA and ZNF385A were also up-regulated in primary tumor cells from patient 32 after co-culture with N-MSCs." (PMID 29503225, 2018). "We used the Tumor Immune Dysfunction and Exclusion (TIDE) score to assess the efficacy of immunotherapy in different ZNF385A and ZNF346 subgroups." (PMID 36834567, 2023). "According to the Tumor Immune Estimation Resource (TIMER) database, ZNF385A and ZNF346 were significantly positively correlated with six main infiltrating immune cells in HCC, such as B cells, CD8 T cells, CD4 T cells, macrophages, dendritic cells, and neutrophils." (PMID 36834567, 2023).
cancer (2 papers, 2023 to 2024). A tumor composed of atypical neoplastic, often pleomorphic cells that invade other tissues. "By this mode of action, ZNF385A was shown to be involved in processes related to cell cycle control and cancer progression." (PMID 39408753, 2024). "We first investigated the pan-cancer expression patterns of ZNF385A and ZNF346 via the Cancer Genome Atlas (TCGA) and Genotype Tissue Expression (GTEx) datasets." (PMID 36834567, 2023). "As the VEGF signaling pathway was enriched in the ZNF385A- and ZNF346-high groups, we predicted the chemotherapeutic response of sorafenib for each sample, based on the Genomics of Drug Sensitivity in the Cancer (GDSC) database." (PMID 36834567, 2023). "ZNF385A and ZNF346 both belong to RNA binding proteins, and they have very similar structures; however, there are very few studies in cancers." (PMID 36834567, 2023). "ZNF385A and ZNF346 were also ubiquitously expressed in a variety of cancer cell lines, based on the screening of expression data from the Cancer Cell Lineage Encyclopedia (CCLE) dataset." (PMID 36834567, 2023). "This provoked us to explore whether ZNF385A and ZNF346 are involved in cancer initiation and progression." (PMID 36834567, 2023).
ZNF385A also shares sentences with these, for which no sentence is quoted: adenocarcinoma (1 paper); hepatocellular carcinoma (1); leukemia (1); liver cirrhosis (1); Pan (1); thymoma (1); uveal melanoma (1).